CD47 (CD47 molecule)
Diseases named in the same sentence as CD47 in open-access papers (continued):
Sharing a sentence is not in itself a finding about the gene and the disease.
tumor (continued). "One strategy to circumvent this issue is by reducing the bsAbs affinity for CD47 but retaining the ability to block the CD47-SIRPα interaction and elevating the affinity to a second tumor antigen." (PMID 34305918, 2021). "CD47 is an antiphagocytic transmembrane protein that is upregulated on tumor cells to initiate immune escape." (PMID 34041034, 2021). "Blocking SIRPα-CD47 interactions alleviates inhibitory signaling resulting in improved tumor cell clearance." (PMID 33936033, 2021). "This strategy was used in a study of glioblastoma, where it was observed that a CD47 monoclonal antibody converted tumor-promoting TAMs to an anti-tumor phenotype that exhibited enhanced phagocytosis of cancer cells." (PMID 34178692, 2021). "Further studies by Wang and Steinmetz (2019) found that a protein known as CD47, that is widely expressed on tumor cells, prevents the action of T cells and phagocytic cells." (PMID 34976959, 2021). "This enhancement in tumor cell killing of CD47 KO cell lines happened similarly upon a longer stimulation overnight of the neutrophils with either GM-CSF or G-CSF cytokines." (PMID 34503071, 2021). "Inhibiting the CD47-SIRPα signaling pathway enhances the phagocytosis of tumor cells by macrophages." (PMID 33671658, 2021). "Cluster of differentiation 47 (CD47) is a trans-membrane protein ubiquitously expressed on human cells but overexpressed on many types of tumor cells." (PMID 34717705, 2021). "Tumor Immune Single-cell Hub (TISCH) single cell database was employed to evaluate correlation of CD47 with tumor microenvironment." (PMID 34966389, 2021). "The tumor cell response to damage induced by ionizing radiation provides such a signal to enhance CD47-induced tumor clearance in immune-competent mice." (PMID 33925464, 2021). "These biomimetic MNPs efficiently accumulated in the TME under external magnetic field guidance and specifically blocked the macrophage-inhibiting CD47–SIRPα binding between tumor cells and macrophages." (PMID 34675914, 2021). "The binding of aberrantly expressed CD47 on tumor cells to signal regulatory protein-alpha (SIRPA) on macrophages allows tumor cells to evade immune destruction." (PMID 33799989, 2021). "Highly efficient secretion, CD47 blocking, and tumor eradication by immune cell activation are demonstrated." (PMID 34729396, 2021). "As to its role in tumour development, CD47, which is an ubiquitously expressed surface receptor in all types of cancers, acts as an antiphagocytic “don't eat me” signal, binding to SIRPα on the macrophages and dendritic cells." (PMID 34093795, 2021). "Gene-expression data identified a potential mechanism for this apparent protective function and suggested that high CD47 expression increases NK cell recruitment into the tumor microenvironment." (PMID 33925464, 2021). "So far, CD47 is the only immune checkpoint that can be considered to inhibit macrophage phagocytosis, which renders anti-CD47 therapies different from others that target immune checkpoints to inhibit tumor metastasis." (PMID 34367975, 2021). "Preliminary results showed that IBI322 had higher efficacy in vivo, tumor-rich distribution and better safety than the mono-specific anti-CD47 antibody." (PMID 34305918, 2021). "These hybrid nanovesicles, termed hGLVs, can also improve the macrophages-mediated the phagocytosis of tumor cells by blocking CD47 signal, and induce immunogenic cell death during photothermal therapy." (PMID 34852849, 2021). "Silencing of CD47 to remove the ‘don't eat me signal’ whilst also silencing CD73 on tumor to increase the accumulation of anti-tumorgenic M1 macrophages." (PMID 34688033, 2021). "After the role of CD47 in the process of tumor cell evasion from the immune system had been disclosed, targeting CD47 has become a novel strategy for treatment, and various anti-CD47 antibodies have been reported, such as Hu5F9-G4, ZF1, B6H12 antibodies, etc.." (PMID 33917794, 2021).
tumor (continued). "Multiple pro- and antiphagocytic signals play a role in the endocytosis of tumor cells and NPs can be beneficial as codelivery agents of two signal modulators, such as to suppress CD47–SIRPα interactions and enhance CRT presence at the tumor." (PMID 33748077, 2021). "It is important to point out that targeting CD47 on tumors can immensely enhance anti-tumor effect of other therapeutic strategies." (PMID 34717705, 2021). "Tumor cells hijack this signaling mechanism and overexpress CD47 to evade the immune system and enhance survival." (PMID 34471125, 2021). "On the other hand, using exosome-SIRPa, which is the ligand of CD47, is sufficient to increase the tumor cell phagocytosis and prime an antitumor T cell response." (PMID 34830787, 2021). "Anti-CD47 therapies block CD47-SIRPα interaction and restore phagocytosis, consequently increasing macrophage-related anti-tumor activity." (PMID 34944878, 2021). "Tumor immunotherapies based on CD47/PD-L1 blockade have shown strong antitumor effects and have been demonstrated to prolong survival when used in the treatment of various tumors." (PMID 33731702, 2021). "The specific targeting, drug delivery, and anti-tumor efficacy of the anti-CD47 ADC were investigated in vitro and in vivo." (PMID 34452008, 2021). "As shown in the volcano plot, SU decreased GZMB expression and upregulated genes related to inflammatory activation (FOS, JUN, NFKBIA, DUSP2, JAK1, PIM1), tumor immunity (CD47, PCBP2, EIF5A, PDIA3, EGR1), and DNA damage (H2AFX, DDIT3, GADD45B)." (PMID 34824394, 2021). "Some studies reported that phagocytosis of tumour cells by phagocytes was inhibited because of the interaction between CD47 on the tumour surface and the signal regulatory protein (SIRPalpha) on macrophages." (PMID 33511212, 2021). "Blockade of CD47 signaling triggers the immune system, reactivates phagocytosis and promotes tumor eradication." (PMID 34966389, 2021). "In future studies, more strategies by targeting CD47 and its ligands specifically on tumor cells should be investigated." (PMID 34305918, 2021). "In the study, NP-siCD47/CCL25 remarkably increased the invasiveness of CCR9+CD8+ T cells, inhibited the expression of CD47 in tumor cells, and inhibited tumor cells metastasis and growth by T-cell-dependent immunity." (PMID 34490243, 2021). "In mice, CD47 blockade contributed toward increased activation and cytotoxic potential of tumor-infiltrating CD8+ T cells." (PMID 34603322, 2021). "To functionally test this, we implanted E0771 cancer cells into the mammary gland of C57Bl/6 mice deficient in T, B and NK cells [Rag2−/−::Cd47−/−::Il2rg−/−; triple knockout (TKO)] and compared the tumor growth to tumors in WT C57Bl/6 mice." (PMID 33653826, 2021). "Tumor cells secrete exosomes highly enriched CD47, which promoted metastasis and facilitated a microenvironment for tumor progression." (PMID 33867849, 2021). "Based on the crucial role of CD47-SIRPα axis in tumor immune escape, clinical trials of anti-CD47 antibodies are under way, involving drugs such as Hu5F9-G4, HX009 and AK117." (PMID 34717710, 2021). "CD47 is a “don’t eat me” signal present on the membrane of many tumor cells and EVs; thus, it can protect cells and EVs from phagocytosis by monocytes and macrophages." (PMID 34830787, 2021). "A recent study demonstrated that IBI322 selectively bound to CD47+PD-L1+ tumor cells, effectively inhibited CD47-SIRPα signal and triggered strong tumor cell phagocytosis in vitro, but only with minimal impact on CD47 single positive cells such as human RBCs." (PMID 34717705, 2021). "In vivo studies have shown that blocking CD47 enhances the phagocytosis of macrophages and cytoplasmic sensation of tumor cell DNA, thereby activating the innate immunity through the STING signal and activating T cells through DCs." (PMID 34363319, 2021).
tumor (continued). "Enhanced macrophage clearance of tumor cells damaged by irradiation was a plausible mechanism to account for the synergism we observed between radiation and CD47 knockdown in syngeneic tumor models." (PMID 33925464, 2021). "The best characterized therapies targeting this checkpoint are anti-CD47 antibodies, which have proven effective in inducing phagocytosis of tumor cells in vitro as well as inhibiting growth of both hematologic and solid tumors." (PMID 34584838, 2021). "The broken benzoic-imine bonds are cleaved to release antibodies of SIRPα and CD47 in the acidic TME abolished the “don’t eat me” signal between tumor cell and macrophages." (PMID 34062992, 2021). "Elevated CD47 expression on tumor cells is now recognized as a general mechanism to evade host innate immunity for various solid tumors and hematologic malignancies." (PMID 33925464, 2021). "Combining anti-CD47 blocking antibody with rituximab has elicited synergistic anti-tumor activity in pre-clinical models and early clinical results have been promising." (PMID 33842331, 2021). "Incubation of GEM with each cell line increased the expression of HLA-class I, PDL-1 and CD47 on each tumour cell line." (PMID 32661823, 2021). "An oncolytic VV engineered to counteract anti-phagocytic CD47, replicated in tumour cells and redirected both M1 and M2 macrophages to tumour cells in vitro." (PMID 34452439, 2021). "Anti-CD47 treatment elevates the number of TAMs in an ovarian cancer model, yet still resulting in a reduction of tumor cell numbers and an increase in survival." (PMID 34572939, 2021). "The interaction between CD47 and SIRPalpha was antagonized using SIRPalpha-exosomes to promote phagocytosis of the tumour cells." (PMID 33511212, 2021). "The effects of a CD47/SIRPα blockade by azelnidipine were further explored in the MC38 tumor model, which has a large quantity of intratumoral macrophages and was widely used for the CD47 targeted anti-tumor study." (PMID 34068552, 2021). "Incubation with an anti-CD47 antibody induced phagocytosis of bladder tumor cells by macrophages, inhibiting primary tumor growth and preventing tumor metastasis in vivo." (PMID 34572939, 2021). "3D tumor spheroids were used to evaluate NTP effects on surface CD47, as spheroids better represent the pathophysiological development of cancer cells compared to 2D monolayers." (PMID 33540720, 2021). "At the same time, several reports pointed out a putative overestimation of the CD47:SIRPα interaction in the interpretation of CD47-mediated modulation of anti-tumor immune response." (PMID 34638503, 2021). "Its ligand, CD47, a molecule present on normal cells that generally acts as a ‘don’t eat me signal’, is often overexpressed by tumor cells, leading to an evasion of tumor cell recognition and hampered elimination by the immune system." (PMID 34503071, 2021). "CD47/Signal regulatory protein α (SIRPα) is a crucial immune checkpoint pathway that is crucial for maintaining self-stability and eliminating tumor cells." (PMID 34943817, 2021). "Recently, the fully human anti-CD47 IgG4 antibody TJC4 (TJ011133) was shown to specifically block the CD47-SIRPα axis, enhancing phagocytosis in a set of tumour cell lines and AML primary cells." (PMID 33430146, 2021). "For example, increased expression of CD47 by tumor cells triggers an inhibitory signaling in macrophages through the immune checkpoint SIRPα, that limits macrophage-dependent phagocytosis and lymphocyte chemotaxis." (PMID 34276698, 2021). "In intratumoral transfection experiments, CD47 blockage and increased migration of macrophages into the tumor were observed within 17 h of a single injection." (PMID 34729396, 2021). "Most tumors harbor surface CD47 that interacts with signal-regulating protein α (SIRPα) on phagocytes, which reduces the ability of macrophages to phagocytose tumor cells." (PMID 33537081, 2021).
tumor (continued). "A study on glioblastoma found that CD47 blockade can enhance the phagocytic ability of macrophages and induce TAMs transform into an anti-tumor state." (PMID 34625124, 2021). "Activation of CD47 on tumor cells can also lead to caspase-independent cell death induction, although the exact molecular mechanisms are still not completely understood." (PMID 33805268, 2021). "More recently, after the molecular mechanism of the role of CD47 in the process of tumour cell escape from immune recognition was elucidated, targeting CD47 has become a novel approach for treatment and has changed the method of cancer immunotherapy." (PMID 33449453, 2021). "Cancer cells expressing CD47 stimulate macrophage SIRPα to generate a “don’t eat me” signal to evade phagocytosis, and the SIRPα/CD47 signaling axis is now a well-established checkpoint in tumor immunity." (PMID 34899748, 2021). "Although CD47 was upregulated on tumor cells, its ubiquitous expression on the normal cell, especially the hematopoietic cells, has been a major concern for CD47-targeted therapy." (PMID 34068552, 2021). "The mechanism of antitumor synergy with 5F9 and rituximab therapy depends largely on macrophage-mediated tumor killing through the blockade of the antiphagocytic CD47 signal by 5F9 combined." (PMID 33562694, 2021). "Expression of CD47 helps the tumor cells escape from elimination by macrophages and facilitates their metastasis." (PMID 34625564, 2021). "IHC staining showed that CD47 was primarily located in cytoplasmic membrane of tumor cells and to a lesser extent diffusely in cytoplasm." (PMID 34195295, 2021). "Our results showed that VES (I) and VES (II) concentrations significantly inhibited CD47 mRNA and protein expression in the tumours of the mice under examination." (PMID 34093795, 2021). "CD47 and SIRPα expression depend on the tumor histotype with a high frequency of expression in DDLPS and chordoma, as assessed by immunohistochemistry." (PMID 34925348, 2021). "Monoclonal antibodies blocking the interaction between CD47 on tumor cells and SIRPα on innate immune cells is another interesting direction for future research." (PMID 34094963, 2021). "By transforming bacteria with a plasmid that encodes a synchronized lysis circuit (SLC) molecule plus a nanobody antagonist of CD47 (CD47nb), the authors were able to selectively release the therapeutic agent in to tumour cells in vivo." (PMID 34658896, 2021). "First, we expect sCV1-hIgG1 to be quickly absorbed by transfected and adjacent tumor cells, as they express high amounts of CD47, limiting a further spread." (PMID 34729396, 2021). "Azacytidine increases the expression of CD47, which leads to the increased binding of magrolimab to CD47, which ultimately results in the increased phagocytosis of tumour cells by macrophages." (PMID 34439269, 2021). "CD47-induced SIRPα signaling in macrophages and dendritic cells indirectly enhances anti-tumor adaptive T cell immune responses." (PMID 33925464, 2021). "Anti-CD47 treatment shifts the phenotype of macrophages toward the anti-tumoral subtype, leading to enhanced tumor cell phagocytosis by both anti-tumoral and pro-tumoral macrophage subtypes with a higher phagocytosis rate caused by anti-tumoral macrophages." (PMID 34071306, 2021). "The idea that CD47 antibodies, such as B6H12, can prevent this interaction, and thus, enable macrophages to phagocytize CD47‐expressing tumor cells suggests that the RS17 peptide can produce the same effect." (PMID 33629544, 2021). "It seems that anti-CD47 blockade increases the phagocytosis of tumor cells and the secretion of cytokines and chemokines, which promote macrophage recruitment." (PMID 34572939, 2021). "Given the widespread expression of surface CD47 in tumors, we tested if other tumor cell lines respond to BoxA with a decrease in CD47 surface exposure." (PMID 33956406, 2021).
tumor (continued). "In light of these findings, TDEs harboring CD47 are assumed to play crucial roles in the tumor escape from immune cells." (PMID 34078376, 2021). "Global gene-expression profiling in NK cells from tumor-bearing mice identified CD47-dependent transcriptional responses that regulate systemic NK activation and exhaustion." (PMID 33925464, 2021). "Therapeutic targeting of CD47, a surface glycoprotein and “don’t eat me” signal expressed on immune and tumor cells, which interacts with SIRPα on macrophages to suppress phagocytosis, is also being investigated." (PMID 33572196, 2021). "The affinity of RS17 for CD47‐expressing tumor cells was determined, while the inhibition of CD47‐SIRPα signaling was evaluated in vitro and in vivo." (PMID 33629544, 2021). "Another mechanism of tumor immune evasion is CD47, a critical “don’t eat me” signal for the innate immune system and regulator of the adaptive immune response that is over-expressed on the surface of most tumors." (PMID 34573091, 2021). "A preclinical study in which human tumor cells were co-cultured with SIRPαFc (TTI-621) that binds to CD47 demonstrated the anti-tumor effect of CD47-blockade on various solid and hematologic malignancies." (PMID 33669431, 2021). "Further studies are needed to evaluate the prognostic role of CD47 as an independent factor, in which other prognostic factors, such as tumor stage, are excluded." (PMID 33917794, 2021). "Based on our data, we propose that BTLA can be a target of tumor immunotherapy alone or in combination with anti-CD47." (PMID 34885092, 2021). "Some preclinical studies have shown that in tumor models, anti-CD47 antibody treatment not only promoted the phagocytosis of cancer cells by macrophages, but also induced an antitumor cytotoxic T cell immune response." (PMID 34683963, 2021). "Tumor CD47 expression has been suggested to contribute to immune evasion by tumor cells through the CD47–SIRPA axis." (PMID 33799989, 2021). "Magrolimab is a first-in-class immune checkpoint inhibitor targeting CD47 that eliminates tumor cells through macrophage phagocytosis." (PMID 34068316, 2021). "If the tumor cells express CD47, it binds to SIRPα on phagocytic immune cells, preventing engulfment." (PMID 33802565, 2021). "In the present study, we showed that NTP operated at the same ICD-inducing regime can also increase tumor immunogenicity by reducing the immunosuppressive signal, CD47." (PMID 33540720, 2021). "In this process, cytosolic DNA sensor STING (Stimulator of interferon genes) is required for anti-CD47 antibody-mediated tumor regression." (PMID 34512146, 2021). "The expression of CD47 is related to tumor growth and is proposed to be a critical clinical prognostic factor and mortality." (PMID 34189144, 2021). "Data from several types of cancers have illustrated the positive correlation between high expression of CD47 in tumor cells and poor prognosis." (PMID 33765961, 2021). "Hu5F9-G4 (5F9) is a humanized anti-CD47 mAb therapy to augment phagocytosis of tumor cells and induce T-cell response by cross-presentation of tumor antigens by macrophages." (PMID 34765437, 2021). "We also aimed to unravel the role of macrophages after sCV1-hIgG1-mediated CD47 blocking in vivo and observed significantly increased tumor infiltration at 17 h after transfection." (PMID 34729396, 2021). "An injectable double-layer-gel matrix of sorafenib and anti-CD47 antibody efficiently prevented tumor recurrence and metastasis in in vivo 4T1 mice models." (PMID 35111673, 2021). "Targeting “Don't eat me” signaling pathway such as blocking the CD47-SIRPα interaction can improve macrophage phagocytosis of tumor cells." (PMID 33763066, 2021). "Targeting CD47 alone or in combination with anti-PD-L1 resulted in decreased tumor burden and increased intratumoral granzyme B secreting CD8 + T cells in a TNBC murine model." (PMID 34078406, 2021).